HNRNPA1 (heterogeneous nuclear ribonucleoprotein A1)
Diseases named in the same sentence as HNRNPA1 in open-access papers (continued):
Sharing a sentence is not in itself a finding about the gene and the disease.
gastric cancer (continued). "SNHG8 in the cytoplasm interacts with hnRNPA1 and enhances its stability by binding to HNRNPA1, thus increasing the level of TROY and damaging DNA damage repair in gastric cancer cell lines during chemotherapy." (PMID 38927012, 2024). "In gastric cancer, cisplatin and PTX induce CAFs to secret miR‐522 by activating the USP7 (ubiquitin‐specific protease 7)/hnRNPA1 (heterogeneous nuclear ribonucleoprotein A1) axis." (PMID 36253096, 2022). "It has been reported that hnRNPA1 was highly expressed in gastric cancer tissues, which promote proliferation, migration and EMT of gastric cancer cells." (PMID 32915499, 2020). "The results identifying a new signal pathway miR-let-7a/c-Myc/hnRNPA1/PKM2 suppresses the growth and proliferation of gastric cancer, providing new insights into the pathogenesis of gastric cancer and evolvable the therapeutic strategies." (PMID 26745603, 2016). "Using mass spectrometry of clinical samples from gastric cancer, Zhang and his team found that the levels of ALOX15 decreased, but the levels of ubiquitin-specific protease 7 (USP7) and heterogeneous nuclear ribonucleoprotein A1 (hnRNPA1) increased significantly in tumour tissue." (PMID 38166927, 2024). "Moreover, hnRNPA1 promoted cell invasion by inducing EMT transition and was a promising molecular target in gastric cancer cells." (PMID 35875075, 2022). "Therefore, we studied the action of AC on the endoplasmic reticulum stress in gastric cancer and proved that AC strengthened the levels of GRP78 and Chop and suppressed the hnRNPA1 level." (PMID 35692504, 2022). "Interestingly, high expression of hnRNPA1 has also been shown to promote EMT, at least in gastric cancer." (PMID 32417965, 2020). "Currently, it was well documented that hnRNPA1 could be recruited by USP7 to facilitate exo-lncFERO and exo-miR-522 secretion, aiding their regulating of lipid metabolism, ferroptosis and individual chemosensitivity gastric cancer (GC) cells." (PMID 35879279, 2022).
breast cancer (32 papers, 2014 to 2024). A primary or metastatic malignant neoplasm involving the breast. "Hnrnpa1 controls the splicing of a wide variety of transcripts and is highly expressed in breast cancers, where it is associated with metastatic progression." (PMID 34344445, 2021). "A previous study has shown that LIN28A in nuclear extract is associated with HNRNPA1, a key splicing regulatory factor, in breast cancer cells." (PMID 34816099, 2021). "HNRNPA1, regulated by miR-503 and miR-424, is associated with breast cancer cell proliferation (Otsuka, Yamamoto & Ochiya, 2018)." (PMID 31576243, 2019). "In ErbB-2 transformed MDA-MB-231 breast cancer cells nuclear TβR1 interacts with hnRNPA1, which serves as a cofactor for the association with purine-rich RNA sequences." (PMID 31416165, 2019). "HNRNPA1 is linked to tumorigenesis and tumor progression and has been shown to be up-regulated in a wide spectrum of cancers, such as breast cancer, colorectal cancer, lung cancer, and glioma." (PMID 29872500, 2018). "Next, to evaluate the prognostic value of HNRNPA1 expression in basal-like breast cancer, we investigated the association between HNRNPA1 expression in breast cancer samples and disease progression (for other types of breast cancer)." (PMID 29872500, 2018). "We then analyzed the presence of SK molecules associated with intracellular hnRNPA1 protein, which was pulled down from the crude protein extract of human mammary tumor cells (MDA-MB-231), using anti-hnRNPA1 antibody-conjugated magnetic beads." (PMID 27248319, 2016). "For example, overexpression of hnRNPA1 has been reported from gliomas, lymphomas, myelomas, leukemias, and breast, colorectal, gastric, and lung cancers, and was linked to poor prognosis in hepatocellular carcinoma and breast cancer." (PMID 32417965, 2020). "However, overexpression of hnRNPA1 has been previously linked to poor prognosis in hepatocellular carcinoma and breast cancer." (PMID 32417965, 2020). "HNRNPA1 could serve as a therapeutic target in breast cancer, consistent with the Kaplan–Meier analysis showing that high HNRNPA1 levels were associated with poor clinical outcomes in basal-like breast cancer." (PMID 29872500, 2018). "Therefore, the data above showed that, in basal-like breast cancer, HNRNPA1 was associated with poor clinical outcomes and could serve as a viable target for resveratrol/miRNAs in cancer treatment." (PMID 29872500, 2018). "hnRNPA1 exhibits minimal expression in normal tissues, but it is highly expressed in various types of malignancies, including breast cancer, prostate cancer, oral cancer, neuroblastoma, bladder cancer, lung cancer, colon cancer, and hepatocellular cancer." (PMID 38785973, 2024). "For example, hnRNPA1 was overexpressed in lung carcinoma, GC, and colorectal cancer and has been correlated with poor prognosis in hepatocellular carcinoma and breast cancer." (PMID 37897508, 2024). "Resveratrol inhibits the proliferation of breast cancer cells by upregulating miR-424-5p and downregulating heterogeneous nuclear ribonucleoprotein A1 (HNRNPA1)." (PMID 36612314, 2023). "The HnRNP family members HnRNPA1, HnRNPA2, HnRNPI, HnRNPM and HnRNPK have been reported to be highly expressed in breast cancer." (PMID 36052258, 2022).
breast cancer (continued). "The HnRNP family of HnRNPA1 and HnRNPI were reported to be overexpressed in breast cancer and to regulate selective splicing of PKM to promote tumor cell proliferation." (PMID 36052258, 2022). "The isoform switch we describe for HNRNPA1 has implications in breast cancer and possibly other malignancies." (PMID 34961772, 2021). "The stable isoform is expressed more in breast cancers, and more HNRNPA1 protein is synthesized from this isoform." (PMID 34961772, 2021). "In breast cancer patients (n = 856), independent from tumor type, we observed significant downregulation (p < 0.0001) of an HNRNPA1 isoform that ends with a distal poly (A) site on the gene locus (Hs.546261.1.27)." (PMID 34961772, 2021). "In a targeted screen for HNRNPA1 expression in breast cancers, we re-analyzed GSE31519, GSE2034, GSE7390 datasets using APADetect, an algorithm to detect isoform level expression differences based on differential poly(A) site usage." (PMID 34961772, 2021). "Next, to shed light on the possible effects of HNRNPA1 activity in breast cancers, we turned to microRNAs (miRNAs) as a less explored aspect of HNRNPA1 function." (PMID 34961772, 2021). "Overall, we report an isoform switch for HNRNPA1 and provide insight into the oncogenic roles of HNRNPA1 as a versatile RNA-binding protein whose expression is critical for the neoplastic phenotypes of breast cancer cells." (PMID 34961772, 2021). "Next, to begin addressing the biological relevance of HNRNPA1 overexpression in breast cancers, we generated stable shRNA constructs to target HNRNPA1 expression in MCF7 and MDA-MB-231 cells and tested these models for changes in their neoplastic phenotypes." (PMID 34961772, 2021). "Given all the diverse roles of HNRNPA1, we sought to provide additional insight into the HNRNPA1 function in breast cancers." (PMID 34961772, 2021). "Five out of the six splicing factors have been shown before to be overexpressed in breast cancer: HNRNPA1, HNRNPA2B1, HNRNPK, PTBP1 and SRSF6." (PMID 32756364, 2020). "Recent studies have suggested that that HNRNPA1 is involved in the progression and metastasis of several cancers, including lung, stomach, prostate, and breast cancers." (PMID 32595697, 2020). "HNRNPA1 is up-regulated in a wide spectrum of cancers, such as breast cancer, colorectal cancer, lung cancer, and glioma." (PMID 29872500, 2018). "To determine the functional effects of HNRNPA1 on cell proliferation of basal-like breast cancer cells (MDA-MB-231-luc-D3H2LN cells), we knocked down HNRNPA1 using three independent siRNAs." (PMID 29872500, 2018). "By using a combination of antibody pull-down assay and MS/MS analysis, we further biochemically confirmed the binding activity between SK and the hnRNPA1 protein in SK-treated human mammary cancer cells (MDA-MB-231)." (PMID 27248319, 2016). "This is illustrated by the CBX5 down-regulation in metastatic breast cancer cells compared to poorly invasive breast cancer cell lines whereas hnRNPA1 is relatively evenly expressed in both types of cell lines." (PMID 26791953, 2016). "To evaluate the potential universality and importance of hnRNPA1-targeting in these compound-induced ICDs, we also used a siRNA approach to knockdown the hnRNPA1 expression in 4T1 mammary carcinoma cells." (PMID 27248319, 2016). "The in vivo relevance of our findings on the role of S6K2 signalling to the subcellular localisation of hnRNPA1 is supported by our data from immunohistochemistry staining of lung and breast cancer tissue microarrays." (PMID 25324306, 2014). "Previous studies also demonstrated overexpression of hnRNPA1 during breast cancer progression." (PMID 36151122, 2022). "Indeed, most breast cancer cell lines have low “gene effect scores” indicating a high likelihood that HNRNPA1 is an essential gene in depletion assays." (PMID 34961772, 2021). "Here, we describe an isoform switch between the 3′-UTR isoforms of HNRNPA1 in breast cancers." (PMID 34961772, 2021).
breast cancer (continued). "Our work here demonstrates an isoform switch for HNRNPA1 in breast cancers." (PMID 34961772, 2021). "Moreover, breast cancer patients express high hnRNPA1 and low Rac1b levels in normal breast tissue, but low hnRNPA1 and high Rac1b levels in cancer tissue, suggesting that splicing of the Rho GTPase is also in vivo regulated by hnRNPA1." (PMID 31666932, 2019). "The expression analyses supported existence of independent regulation of CBX5 and hnRNPA1 transcription in breast cancer cells with a concordant up-regulation of the two genes from normal cells to cancer cells and subsequently specific down-regulation of CBX5 in metastatic cells." (PMID 26791953, 2016). "Interestingly, immunohistochemical staining of lung and breast cancer tissue samples demonstrated that increased S6K2 expression correlates with decreased cytoplasmic hnRNPA1 and increased BCL-XL expression." (PMID 25324306, 2014). "Additionally, ZMYND11 was found to interact with HNRNPA1 in the lung cancer cell line A549 and the breast cancer cell line MDA-MB-231, indicating that the association between ZMYND11 and HNRNPA1 might be common across different cancer types." (PMID 39341825, 2024). "In breast cancer (BC), hnRNPA1 affect the malignant properties of cancer cells by mediating the CEACAM1-S/-L ratio." (PMID 35879279, 2022). "As a pre-mRNA splicing inhibitor, HNRNPA1 regulates CD44 isoforms, and low levels of HNRNPA1 can significantly inhibit cell invasion and induce cell death in breast cancer." (PMID 35022405, 2022). "RES promotes the epithelial-type alternative splicing of Cd44, Enah, and FGFR2 pre-mRNAs in breast cancer cells by upregulating KH-type splicing regulatory protein (KHSRP) and heterogeneous nuclear ribonucleoproteins A1 (hnRNPA1) expression." (PMID 33937049, 2021). "In breast cancer, colorectal cancer, and prostate cancer cells, PRMT4, PRMT5, and PRMT7 and their mediated hnRNPA1 methylation and splicing isomerism can effectively promote the growth of cancer cells." (PMID 34603017, 2021). "Another possibility in breast cancer cells to mechanistically disconnect generation of HP1α from the functionally shared promoter architecture for CBX5 and hnRNPA1 is the use of downstream alternative promoters producing HP1α coding transcripts." (PMID 26791953, 2016). "To further investigate the role of hnRNPA1 in SK-induced post-transcriptional regulation, we overexpressed the human and mouse hnRNPA1 in human MDA-MB-231 and mouse 4T1 mammary tumor cells, respectively." (PMID 27248319, 2016). "Transient transfection and transposon mediated integration of dual-reporter mini-genes containing the bi-directional hnRNPA1 and CBX5 promoter was performed to investigate transcriptional regulation in breast cancer cell lines." (PMID 26791953, 2016). "Splice factors that are suggested to control the Warburg effect are multiplayers PTBP1, hnRNPA1 and hnRNPA2 which not surprisingly are also involved in breast cancer growth and invasion." (PMID 31666932, 2019). "Finally, expression of hnRNPA1 and CBX5 mRNA isoforms were measured by quantitative reverse transcriptase PCR (qRT-PCR) in breast cancer tissue samples." (PMID 26791953, 2016). "We next analysed the relationship between hnRNPA1, HP1α-V3 and STET mRNA expression in breast cancer samples to see whether this corresponds to observations from breast cancer cell lines." (PMID 26791953, 2016). "Additionally, let-7a-5p maturation is inhibited by hnRNPA1, thus forming a let-7a-5p/Stat3/hnRNPA1 negative feedback pathway in breast cancer cells." (PMID 38785973, 2024). "Thus, for hnRNPA1 and CBX5 evolution must have adapted regulatory mechanisms un-coupling the expression of the two genes under certain cellular environments e.g. during breast cancer metastasis." (PMID 26791953, 2016).
breast cancer (continued). "Moreover, immunohistochemical staining of lung and breast cancer tissue microarray demonstrates that increased expression of S6K2 correlated with increased BCL-XL and decreased cytoplasmic hnRNPA1 levels in tissue samples providing indications of the in vivo relevance of findings." (PMID 25324306, 2014). "The novel HP1α encoding transcriptional isoforms, V1 and V2, could participate in generating relatively higher HP1α expression in non-metastatic MCF7 breast cancer cells without requirement of specific CBX5 to hnRNPA1 transcriptional enhancement from the bi-directional promoter." (PMID 26791953, 2016). "In this study, we find the differential expression of CBX5 in metastatic versus non-metastatic breast cancer cells requires a decoupling from the bi-directional promoter architecture of CBX5 and hnRNPA1, and investigate sequences downstream of the CBX5 promoter as possible mediators hereof." (PMID 26791953, 2016).
prostate carcinoma (20 papers, 2016 to 2025). A carcinoma that arises from epithelial cells of the prostate gland. "We subsequently explored the impact of ZMYND11 on HNRNPA1 function in prostate oncogenesis by conducting forced co-expression of full-length ZMYND11 or a MYND-domain-deleted variant with HNRNPA1 in prostate cancer cells." (PMID 39341825, 2024). "We found a strong association between hnRNPA1 upregulation and unfavorable tumor phenotype and adverse clinical outcome in our set of 14,258 interpretable prostate cancers." (PMID 32417965, 2020). "Regarding the clinical significance of PRMT4, 5, and 7, as well as arginine methylation on hnRNPA1, they were highly expressed in several types of cancers, such as breast, colorectal, and prostate cancer, which is associated with aberrant alternative splicing events." (PMID 33782401, 2021). "Altogether, the underlying mechanism involves downregulation of hnRNPA1 expression, downregulation of AR-V7 expression, antagonizes the signaling pathway of androgen receptors, and desensitizes enzalutamide-resistant prostate cancer cells to in vivo treatment with enzalutamide in mouse xenografts." (PMID 33807174, 2021). "In prostate cancer cells, overexpression of hnRNPA1 was associated with increased levels of the androgen receptor splice variant AR-V7, which is constitutively active even in the absence of androgens and has been implicated in the development of the castration-resistant phenotype." (PMID 32417965, 2020). "A recent study linked overexpression of splicing factors (including hnRNPA1) to hypoxia in PC-3 prostate cancer cells, and the authors hypothesized that alternative splicing of cancer-associated genes may help cells to adapt to low oxygen." (PMID 32417965, 2020). "In fact, the molecular circuitry involving hnRNPA1, NF‐κB2/p52, and c‐Myc, intricately modulates AR‐V7 generation in prostate cancer cells." (PMID 39948708, 2025). "Our findings reveal a novel mechanism by which circSPIRE1, regulated by post-translational modification of hnRNPA1, encodes rtSPIRE1 to activate PI3K/AKT signaling, thereby promoting prostate cancer progression." (PMID 40713830, 2025). "To elucidate hnRNPA1’s role in circSPIRE1 translation, we transfected prostate cancer cells with the dual-luciferase reporter construct containing the circSPIRE1 IRES." (PMID 40713830, 2025). "The expression of heterogeneous nuclear ribonucleoprotein A1 (hnRNPA1) and Sam68 positively correlates with AR‐V7 generation and expression in prostate cancer." (PMID 39948708, 2025). "The study findings indicated that quercetin, a heterogeneous nuclear ribonucleoprotein A1 (hnRNPA1) inhibitor, is highly effective in resensitising enzalutamide-resistant prostate cancer cells to enzalutamide." (PMID 40282556, 2025). "The natural polyphenolic compounds quercetin, esculetin, and tetracaine hydrochloride exert effects on prostate cancer, endometrial cancer, and melanoma by disrupting HNRNPA1 nuclear-cytoplasmic transport." (PMID 39062595, 2024). "In breast and prostate cancer cells, hnRNPA1 weakens programmed cell death by promoting the production of the anti-apoptotic splicing isomer Bcl-x and inhibiting the synthesis of the anti-apoptotic protein cIAP1." (PMID 38785973, 2024). "Collectively, these findings demonstrate that ZMYND11 suppresses aerobic glycolysis in prostate cancer cells by inhibiting HNRNPA1-dependent PKM splicing." (PMID 39341825, 2024). "Analysis of several public datasets corroborated our findings, indicating that prostate cancer patients with higher HNRNPA1 levels experienced quicker disease relapse and metastasis." (PMID 39341825, 2024). "Protein levels of HNRNPA1 were also measured in prostate cancer tumors from mice with prostate-specific deletion of Pten (Pbi–cre; PtenloxP/loxP) compared to normal murine prostate glands, showing increased HNRNPA1 in tumor tissues." (PMID 39341825, 2024).